EGF (epidermal growth factor)
Diseases named in the same sentence as EGF in open-access papers (continued):
Sharing a sentence is not in itself a finding about the gene and the disease.
ovarian carcinoma (continued). "In ovarian cancer cells, epidermal growth factor (EGF) has been shown to induce EGR1 and upregulate SLUG, which can decrease the expression of E-cadherin and then enhance tumor metastasis." (PMID 33842351, 2021). "AQP3 upregulation by EGF promoted cell migration in an ovarian cancer cell line, which was inhibited by curcumin." (PMID 32679804, 2020). "Ovarian cancer cell migration is an important process in multicellular spheroids formation, during which macrophage-secreted EGF promotes ovarian cancer cell migration toward TAMs and adhesion to TAMs." (PMID 32477126, 2020). "Similar to what is observed in carcinoma MCF7 cells and ovarian cancer SK-OV-3 cells; reduction in EGF-mediated invasion was observed in FAS siRNA transfected HTR-8/SVneo cells." (PMID 32703964, 2020). "The expression of COX-2 is regulated by various cytokines in ovarian cancer cells, such EGF, vitamin D, IL-1β." (PMID 32363546, 2020). "Mechanistically, floating ovarian cancer cells drive the production and secretion of EGF by CAFs located at the center region of the spheroids." (PMID 32546182, 2020). "The ovarian cancer cells stimulated by EGF of TAMs underwent EMT through upregulation of N-cadherin and vimentin, activation of EGFR/ERK signaling, and downregulation of IncRNA inhibiting metastasis (LIMT) expression." (PMID 32283687, 2020). "TAMs promote ovarian cancer cell proliferation and migration, spheroids formation, and tumor growth by secreting EGF at early stage of transcoelomic metastasis of ovarian cancer." (PMID 32477126, 2020). "It has been shown that M2-like TAMs in ovarian cancer produced EGF to potentiate cancer cell migration and metastasis." (PMID 32283687, 2020). "For example, it was reported that ROS production is required for epidermal growth factor (EGF)-induced AKT activation in mediating tumor angiogenesis in ovarian cancer cells." (PMID 33081375, 2020). "The epidermal growth factor receptor (EGFR) is critical for proliferation and tumorigenesis in ovarian cancer, with it being reported that EGF activates TRPC3/4/5, thus prompting Ca2+ inflow in HEK293 cells (human embryonic kidney 293 cells)." (PMID 32785177, 2020). "In this study, we found that TRPM7 silencing by specific shRNA significantly decreased the levels of TRPM7 expression and attenuated the EGF-induced migration, invasion and wound healing of ovarian cancer cells in vitro." (PMID 30819230, 2019). "A previous study showed that EGF increases the invasion of ovarian cancer cells through EGR1 upregulation." (PMID 30845713, 2019). "(C, D) Inhibition of TRPM7 expression by MK886 mitigated the EGF-induced migration, invasion and wound healing of ovarian cancer cells." (PMID 30819230, 2019). "Studies from our laboratory used live-cell imaging approaches to examine the role of integrins and integrin-mediated adhesion in ovarian cancer cluster survival in suspension cultures supplemented with epidermal growth factor (EGF) and insulin." (PMID 31817625, 2019). "TRPM7 silencing enhanced the EMT and F-actin expression and mitigated the EGF-enhanced EMT process in ovarian cancer cells." (PMID 30819230, 2019). "In ovarian cancer cell lines, both EGF and BDNF can transactivate the receptors and activate Akt, a downstream target." (PMID 29581842, 2018). "For example, pretreated EGF in overexpression EFGR ovarian cancer cells resulted in increased sensitivity of these cells to cisplatin." (PMID 29470420, 2018). "Even ovarian cancer cells appeared induction of proinflammatory chemokines in EGF- or TNF-responsive manner." (PMID 30034618, 2018). "Metal-based inhibitors that have been tested in models of cancer include AQP3 inhibitors such as NiCl2 and CuSO4, which inhibited EGF-induced cell migration in human ovarian cancer cells." (PMID 29922644, 2018). "As a support, it has been shown that CDCP1 expression is regulated through ERK1/2 recruitment in ovarian cancer cells stimulated with EGF." (PMID 29792166, 2018).
ovarian carcinoma (continued). "The EGF-EGFR axis promotes CDCP1 expression in ovarian cancer models, and bone morphogenetic protein 4 induces CDCP1 in pancreatic cancer cells." (PMID 29792166, 2018). "HER-2/neu is a proto-oncoprotein belongs to the family of epidermal growth factor, overexpressed in various human cancers, including ovarian carcinoma." (PMID 28808311, 2017). "Another mechanism involved is the expression of epidermal growth factor (EGF), which inhibits the TGFβ anti-proliferative effect in primary ovarian cancer cells." (PMID 28758950, 2017). "Cell surface CDCP1 contributes to EGF/EGFR signaling-mediated migration in ovarian cancer with up-regulation of CDCP1 RNA and protein expression." (PMID 28537886, 2017). "EGFR ligands, including EGF, TGFα, and HB-EGF, have all been suggested to enhance ovarian cancer progression and increase tumor cell proliferation." (PMID 27888810, 2016). "Our previous studies have shown that EGF induces ovarian cancer cell migration and invasion by down-regulating E-cadherin expression through a variety of signaling pathways." (PMID 27129169, 2016). "Our findings reveal LSD1 as a promising therapeutic target for preventing the metastasis of ovarian cancer, especially EGF signaling-dependent metastasis." (PMID 26489763, 2015). "In ovarian cancer cells, EGF binds to the EGF receptor (EGFR), thus inducing EMT activation through phosphorylation of the Janus kinase/signal transducer and activator of transcription (JAK/STAT3) pathway." (PMID 26356073, 2015). "In ovarian cancer, increased levels of EGF stimulate IL6 secretion, which promote the mobility and resistance to chemotherapy via the JAK/STAT3, SHP-2/Ras, MAPK, and PI3K/Akt signaling pathways." (PMID 26356073, 2015). "Here, we demonstrate that silence of the PTTG oncogene inhibited the proliferation of ovarian cancer cells and colony formation and interrupted the upstream EGF pathway that promotes ovarian cancer proliferation." (PMID 26516926, 2015). "Expression of Haao was significantly repressed in tumours of EGF transgenic mice and hypermethylation of the coding gene was observed in ovarian cancer." (PMID 25872475, 2015). "The current study focuses on the role of cPLA2 in epidermal growth factor (EGF)-stimulated PAF production in ovarian cancer cells." (PMID 24721622, 2014). "In this study, we used CAOV3 and SKOV3 adenocarcinoma cells, two well-characterized human ovarian cancer cell lines, as models to examine the mechanisms involved in EGF-induced PAF production." (PMID 24721622, 2014). "Together, our data indicated that EGF stimulates PAF production in two human ovarian cancer cell lines." (PMID 24721622, 2014). "The results of this study demonstrate that EGF stimulates the release of PAF from human ovarian cancer cells by acting on the EGF-receptor and transactivating the PAF-receptor." (PMID 24721622, 2014). "Primary ovarian cancer cells were dissociated and placed in uncoated culture flasks in serum-free medium supplemented with EGF, b-FGF, insulin, and BSA." (PMID 25369529, 2014). "Evidence suggests that both PAF and EGF play a significant role in oncogenic transformation, tumor growth, neoangiogenesis and metastasis, including ovarian cancer." (PMID 24721622, 2014). "The signaling pathways invovled in PAF production induced by EGF in ovarian cancer cells were assessed." (PMID 24721622, 2014). "We next investigated the signaling pathway downstream of activated EGFR and PAFR in ovarian cancer cells to elucidate the mechanisms involved in EGF-induced PAF production." (PMID 24721622, 2014). "AG1478 and WEB2086 significantly reduced the EGF-induced increase in PAF levels in both ovarian cancer cell lines." (PMID 24721622, 2014). "In this study, we have shown that the phosphorylation of cPLA2 is stimulated by EGF in ovarian cancer cells." (PMID 24721622, 2014). "This suggests alternative mechanisms for claudin regulation by EGF among the different ovarian carcinoma subtypes in vitro." (PMID 23685873, 2013).
ovarian carcinoma (continued). "For example, EGF enhances cisplatin-induced ovarian cancer cell apoptosis, and the degradation of EGFR is correlated with cisplatin-induced cytotoxicity in head and neck cancers." (PMID 23383347, 2013). "Recently this mechanism of the TJ protein regulation in ovarian cancers was explored by treating both ovarian mucinous and serous cystadenocarcinoma cell lines with EGF." (PMID 23685873, 2013). "We have shown that endogenous E-cadherin plays an important regulatory role in cell invasion and that EGF-induced cell invasion is mediated by the down-regulation of E-cadherin expression in high-grade ovarian cancer cells." (PMID 22479527, 2012). "EGF treatment is known to increase cultured ovarian cancer cell migration, invasion, and proteolytic activity." (PMID 22479527, 2012). "Although EGFR signaling pathways in ovarian epithelial cancer cells have been described, very little has been shown regarding the signaling pathways activated by TGFα and EGF in GCTs." (PMID 23155381, 2012). "In high-grade ovarian cancer cultures, it has been shown that epidermal growth factor (EGF) induces cell invasion by activating an epithelial-mesenchymal transition (EMT)." (PMID 22479527, 2012). "Using a trans-membrane migration assay, we found that EGF stimulated migration in seven ovarian cancer cell lines (same as used in this study), and that this resulted from increased cell surface expression of ligated uPAR." (PMID 22424333, 2012). "EGFR and its ligand, epidermal growth factor (EGF), play critical roles in the progression of ovarian cancer through their effects on cellular proliferation, apoptosis, angiogenesis, and metastasis." (PMID 20064265, 2010). "The epidermal growth factor (EGF) receptor is one such protein target with potential utility in the management of ovarian cancer." (PMID 20066160, 2010). "Consistent with the changes in the expression and localisation of N-cadherin, vimentin and β-catenin, EGF also induced a motile phenotype in ovarian cancer cells as evaluated by wound-healing assay in serum-free medium." (PMID 19088723, 2009). "However, it still remains to be determined if activation by EGF or somatic-activating mutations in the kinase domain of EGFR has any effect on the production of IL-6 or GP130 family of cytokines that can lead to the activated status of STAT3 in ovarian carcinomas." (PMID 19088723, 2009). "In the light of the evidence supporting the activated status of STAT3 in ovarian carcinomas and the role of STAT3 in cell motility and EMT, this study sought to directly examine the role of this pathway in EGF-induced EMT in ovarian cancer cells." (PMID 19088723, 2009). "Transforming growth factor-β (TGF- β) and epidermal growth factor (EGF) are known to promote EMT in ovarian cancer." (PMID 19949545, 2009). "We have previously shown that ovarian surface epithelial cells and ovarian cancer cells undergo EMT in response to EGF." (PMID 19088723, 2009). "The association between STAT3 activation and migratory phenotype of ovarian cancer cells was investigated by EGF-induced epithelial–mesenchymal transition (EMT) in OVCA 433 and SKOV3 ovarian cancer cell lines." (PMID 19088723, 2009). "A specific anti-phosphotyrosine antibody was used in conjunction with an immunoblotting technique in order to detect EGF receptor phosphorylation in ovarian cancer cell lines in the absence and presence of exogenous EGF." (PMID 8695362, 1996). "One hundred and seventy-four samples from 133 patients with ovarian cancer were examined for EGF and TGF alpha." (PMID 1764384, 1991). "M2-like TAM-secreted EGF has been shown to promote metastasis in ovarian cancer." (PMID 40647416, 2025). "Moreover, EGF-triggered ovarian cancer cells secrete PAF and contribute to the hyper-responsiveness of platelets." (PMID 36831623, 2023).
ovarian carcinoma (continued). "Similarly, epidermal growth factor (EGF) stimulation of ovarian cancer cells leads to the localization of MT1-MMP to caveolae and internalization in caveolin-1-positive vesicles." (PMID 36982142, 2023). "Experiments with the EGFR inhibitor AG1478 showed that EGF might promote the progression of ovarian cancer by activating the EGFR-ERK signaling pathway." (PMID 37420173, 2023). "GnRH2 expression is also regulated by EGF in ovarian cancer cells." (PMID 38260130, 2023). "In addition, it was indicated that expression of MMP-9 is increased by mediated of EGF (epidermal growth factor) in ovarian cancer cells." (PMID 35538133, 2022). "The results demonstrated that the induction of EMT could be achieved in ovarian cancer cell lines through treatment with EGF and that returning the cells to normal culture media enabled MET to occur." (PMID 34592589, 2021). "Indeed, it has been shown that a neutralizing anti-EGF antibody can suppress the formation of spheroid in ascites mediated by the attenuated expression of ITGA5 in floating ovarian cancer cells, leading to the prolonged survival period." (PMID 32546182, 2020). "M2-like TAMs may secret EGF to regulate the growth and migration of ovarian cancer cells and the metastasis of ovarian cancer." (PMID 32083005, 2020). "Furthermore, inhibition of TRPM7 expression by MK886 also significantly attenuated the EGF-induced migration, invasion and wound healing of ovarian cancer cells by inhibiting the EMT process." (PMID 30819230, 2019). "Interestingly, KP extract also strongly exhibited the reduction of ovarian cancer cell viability in the presence of EGF, suggesting that KP has potent cytotoxic effects, which overcome the influence of EGF in maintaining cell viability." (PMID 29891015, 2018). "Cross talk between EGF and GnRH-II signaling also appears to promote ovarian cancer metastasis." (PMID 28439256, 2017). "Given the evidence that AREG plays more important roles than EGF in the regulation of ovarian cancer progression, it is interesting and important to examine whether SPRY2 can be regulated by AREG and whether SPRY2 also affects the biological functions of AREG." (PMID 27835572, 2016). "In ovarian cancer, it has been demonstrated that growth factors such as EGF may induce the production of H2O2, while in other cell types, it has also been observed that NGF can cause an increase in H2O2 production." (PMID 26091707, 2016). "In addition to Snail and Slug, we have recently shown that hypoxia-inducible factor-1α, a key regulator of hypoxic responses, also mediates EGF-induced E-cadherin down-regulation and ovarian cancer cell invasion." (PMID 27129169, 2016). "Taken together, our results indicate that EGF-dependent PI3K/AKT activation may contribute to the upregulation of LSD1 in ovarian cancer." (PMID 26489763, 2015). "To determine whether cPLA2 is essential for producing PAF stimulated by EGF in ovarian cancer cells, we first tested for the effects of arachidonyl trifluoromethyl ketone (AACOCF3), a small-molecular inhibitor of cPLA2 on PAF production." (PMID 24721622, 2014). "We have also determined that crosstalk can occur bidirectionally between EGFR and PAFR, suggesting that EGF-induced PAF production could result in positive feedback that acts on the PAF-receptor to promote ovarian cancer progression." (PMID 24721622, 2014). "In the same study, Lim and collaborators analyzed NGAL in ovarian cancer cell lines treated with epidermal growth factor (EGF) indicating that NGAL expression was downregulated in ovarian cancer cell lines undergoing the epithelial to mesenchymal transition (EMT) induced by EGF." (PMID 24742531, 2014). "Together, our data suggest a role for cPLA2 in EGF-induced production in ovarian cancer cells." (PMID 24721622, 2014). "EGF also enhances cell migration of ovarian carcinoma through the induction of IL-6." (PMID 23383347, 2013).
ovarian carcinoma (continued). "Additionally, human ovarian cancer cell lines treated with EGF showed significant increases in expression of proteins associated with invasion (urokinase plasminogen activator and its receptor, and plasminogen activator inhibitor-1)." (PMID 20037743, 2010). "Consistent with this fact, neutralising anti-IL6R partially inhibited EGF-induced migration in OVCA 433 cells, suggesting that EGF-induced migratory phenotype is dependent to a certain extent on the EGF-induced expression of IL-6 in certain ovarian cancer cells." (PMID 19088723, 2009). "Both OVCA 433 and SKOV3 cell lines produced IL-6 endogenously but, in the presence of EGF, the production of IL-6 was increased (P<0.05) in the serum-free medium of both ovarian cancer cell lines, consistent with the mRNA enhancement of IL-6 and IL-6Rα on the cells." (PMID 19088723, 2009). "Interestingly, the production of colony‐stimulating factor‐1 (CSF‐1), hepatocyte growth factor (HGF), and epidermal growth factor (EGF) by ovarian cancer cells, endothelial cells, and TAMs, respectively, and the formation of a paracrine loop was shown to be crucial for metastatic progression." (PMID 38411356, 2024). "The blockade of EGFR might abolish EGF’s promotion of ovarian cancer progression." (PMID 36831623, 2023). "Moreover, EGF stimulation also promoted ovarian cancer cell migration." (PMID 34369236, 2021). "EGF secreted by M2-like TAMs may inhibit the expression of metastasis-inhibiting LIMT (lncRNA inhibiting metastasis) by activating the EGFR-ERK pathway to stimulate tumor progression in ovarian cancers." (PMID 32083005, 2020). "Specific neutralizing antibodies directed against four agents known from the literature to cause EMT—that is, EGF, HGF, IGF-1, and TGF-β1—were added to the malignant ascites to establish whether some of these agents may be responsible for EMT development in ovarian cancer cells." (PMID 30609691, 2019). "Therefore, we further tested whether PTTG knockdown in ovarian cancer cells still had proliferation ability after stimulation with EGF." (PMID 26516926, 2015). "We now show that the activation of JAK2/STAT3 may be a pre-requisite for EGF-induced EMT in these ovarian cancer cell lines, as pharmacological inhibition of JAK2 in ovarian cancer cells not only led to an inhibition of STAT3 activation but also inhibition of EGF-induced EMT phenotypes." (PMID 19088723, 2009). "To further understand the contribution of MMP9 to EGF-stimulated metastatic behavior, we created MMP9-null cells (M9-KO) from an ovarian cancer cell line." (PMID 41732872, 2026). "Secondly, the top six genes, each with more than 100 publications (KIT, EGF, STAR, GAL, FGF2, VIP), have known established roles in ovarian cancer." (PMID 40699804, 2025). "AREG autocrine loops are activated in breast and ovarian cancer, and ectopic expression of AREG can induce an AREG/EGFR autocrine loop, rendering T cells EGF-independent." (PMID 38727313, 2024). "Studies have demonstrated that in the ovarian cancer cell line OVCAR3, LAMP1 is upregulated 1.84 times after 24 hours of epidermal growth factor (EGF) treatment but downregulated after 48 hours of exposure." (PMID 39669571, 2024). "Activated platelets release molecules and growth factors such as EGF, PDGF, TGF-β, IGF and CCL5 to promote the expansion of ovarian cancer cells, protecting tumor cells from chemotherapy." (PMID 39707577, 2024). "These TAMs secreted epidermal growth factor (EGF), which increased surface adhesion molecules on both TAMs and ovarian cancer cells, further promoting the adhesion between the two cell types." (PMID 35574025, 2022). "A previous study reported that EGF and BDNF promote metastasis and proliferation of ovarian cancer cells by transactivating TrkB and EGFR, respectively." (PMID 35898394, 2022).